AHCY (adenosylhomocysteinase)
Diseases named in the same sentence as AHCY in open-access papers (continued):
Sharing a sentence is not in itself a finding about the gene and the disease.
urothelial carcinoma (1 paper, 2018). A malignant neoplasm derived from the transitional epithelium of the urinary tract (urinary bladder, ureter, urethra, or renal pelvis). "Second, we have documented here DNA methylation of the 5′-regulatory region of AHCY encoding S-adenosylhomocysteine hydrolase in urothelial carcinoma specimens." (PMID 29472622, 2018). "Here, using two independent techniques for detecting DNA methylation, we observed DNA hypermethylation of the 5′-regulatory regions of the key methyl group metabolism genes ODC1, AHCY and MTHFR in early urothelial carcinoma." (PMID 29472622, 2018).
cancer (35 papers, 2009 to 2025). A tumor composed of atypical neoplastic, often pleomorphic cells that invade other tissues. "Metabolomics revealed the depletion of several metabolites that have homocysteine as a precursor, which was consistent with the lower activity of the methionine cycle caused by lower expression of the AHCY gene in cancer cell lines." (PMID 37299011, 2023). "Alterations in AHCY function have been linked to cancer with varying outcomes depending on the cancer entity involved." (PMID 32408898, 2020). "Thus, the investigation of this relationship may help elucidate the molecular mechanisms underlying the effect of AHCY on cancer cell behavior and may contribute to a better understanding of the pathogenesis of AHCY deficiency-related diseases." (PMID 38003292, 2023). "Although this mechanism is valid for all other previously reported AHCY-related cancer studies, it has yet to be determined which cancer types are highly sensitive to increases in DNA damage caused by AHCY knockdown and which AHCY inhibitors could be used in advanced and targeted cancer therapy." (PMID 30228286, 2018). "In conclusion, targeting methionine metabolism via MAT2a or AHCY inhibition is a possible avenue to arrest cancer progression and improve outcomes for GBM patients." (PMID 40015640, 2025). "Between transcripts linked to the first phase, the AHCY (encodes adenosylhomocysteinase), CYP2B7P1 (encodes cytochrome P450 2B7P1), and DPEP1 (encodes dipeptidase 1) expression increased with cancer growth in subsequent stages of the disease." (PMID 41465541, 2025). "First of all, the MCF-7 and BCC cell lines showed lower internal methionine, taurine and hypotaurine levels, which, together with the down-regulation of AHCY (adenosylhomocysteinase), reveals decreased activity of the methionine cycle in cancer cells." (PMID 37299011, 2023). "This exciting result places AHCY inhibitors as potential agents to target metabolic dependencies in some cancer types." (PMID 33869213, 2021). "Based on these reports, the involvement of AHCY in the molecular mechanisms of cancer is undisputable." (PMID 30228286, 2018). "Recent studies have indicated a functional connection between cancer and S-adenosylhomocysteine hydrolase (AHCY) activity, particularly in liver cancer." (PMID 30228286, 2018). "Adenosylhomocysteinase (AHCY) enzyme that produces L-homocysteine and adenosine by hydrolysis of S-adenosyl-L-homocysteine was found to be overexpressed in cancer." (PMID 25243088, 2014). "AHCY inhibition was reported to reduce cancer cell proliferation." (PMID 41163796, 2025). "Indeed, we have established a new link between S-adenosylhomocysteine hydrolase and cancer cell signaling by analyzing differentially expressed pathways in AHCY deficient SW480 cells." (PMID 38003292, 2023). "Cancer cells are highly dependent on methionine metabolism and several studies report AHCY as a possible therapeutic target, so global protein b-hydroxybutyrylation could play a significant role in the metabolic adaptation of cancer." (PMID 37614745, 2023). "As this suggests that AHCY is a rate-limiting factor for DNA methylation maintenance, its role during epigenomic reprogramming throughout embryo development and/or in disease progression, such as cancer, must now be investigated." (PMID 33869213, 2021). "The overexpression of AHCY on the transcriptional and protein level in the DZNep-resistant clone is consistent with the knowledge of drug resistance in cancer stemming from alterations in the drug target, particularly, alterations involving modified enzyme expression." (PMID 32408898, 2020). "Few studies have investigated the regulation of AHCY expression and its involvement in cancer." (PMID 27041671, 2016). "Therefore, our study further expanded the understanding of the roles of AHCY in cancers." (PMID 35927991, 2022). "In addition, stable knockdown experiments of AHCY have revealed its critical role in cancers." (PMID 35927991, 2022).
cancer (continued). "Finally, we strongly suggest including the AHCY gene in any mutational screens as a potential risk factor for cancer, as, to our knowledge, it is not yet considered in commercially available cancer panels for personal health genomics." (PMID 30228286, 2018). "We demonstrate that both MAT2a and AHCY are required for proper mitochondrial function in GBM and are necessary to protect cancer cells against oxidative damage." (PMID 40015640, 2025). "Recently, functional connections between S-adenosylhomocysteine hydrolase (AHCY) activity and cancer have been reported." (PMID 30228286, 2018). "CRC is related to significant copy number modification in microsatellite stable (MSS), CpG island methylator phenotype- (CIMP-) negative CRCs, including the cancer-related genes, adenosylhomocysteine hydrolase (AHCY), and the upregulation of AHCY gene demonstrating a good correlation." (PMID 35578598, 2022). "Upregulated AHCY gene expression is seen in BRCA, COAD, COADREAD, LIHC, LUAD, LUSC, and STAD that may indicate the transmethylation reactions have a more active state in these cancer types." (PMID 31828117, 2019).
tumor (22 papers, 2009 to 2025). "AHCY was initially identified as a tumor suppressor, and the mRNA expression of AHCY was found reduced in many solid cancer tissues." (PMID 35927991, 2022). "Altogether, AHCY overexpression induced cell proliferation, colony formation, invasion, and tumor angiogenesis, whereas its knockdown impaired its oncogenic function." (PMID 35927991, 2022). "While AHCY is a potential target for tumor therapy, BHB inhibits AHCY through Kbhb modification of the rate-limiting methionine cyclase AHCY K188, K389, K405, site-inhibit AHCY activity." (PMID 36172354, 2022). "In agreement with a tumor suppressor role, AHCY mRNA expression was found to be reduced in a large number of different solid tumor samples as compared with non-tumor paired tissue." (PMID 33869213, 2021). "Taken together, these observations actually hint at a tumor suppressor function for AHCY, which is largely unexplored." (PMID 29472622, 2018). "It is interesting to note that this analysis did not indicate any predicted activation relationships; rather, relationships related to inhibition (for seven proteins: LMNA, NME1, PKM, S100A4, SERPINA1, VIM, and AHCY) were indicated for both increased and decreased proteins in the tumor." (PMID 35512017, 2022). "Moreover, knockdown of AHCY inhibited SW620 cell-induced tumor angiogenesis, while AHCY overexpression promoted DLD-1 cell-induced tumor angiogenesis." (PMID 35927991, 2022). "Adenosylhomocysteinase was initially defined as a tumor suppressor." (PMID 33869213, 2021). "It is also worth further investigation to see whether the translational inhibition of AHCY could be another way of suppressing tumour cell growth by inhibiting mRNA cap methylation and translation." (PMID 27041671, 2016). "Multi-omics analyses revealed consistently elevated expression of AHCY, BUD23, LCMT1, MARS1, METTL6, SCLY and SEPHS1 in various tumor types." (PMID 41441975, 2025). "Here, we demonstrate that AHCY is overexpressed in ESCC, enhances LDHA stability and glycolytic activity, and its inhibition suppresses ESCC proliferation and tumor growth." (PMID 41163796, 2025). "AHCY deficiency’s impact on methylation capacity may have downstream effects on gene expression, possibly influencing the Wnt signaling pathway and the role of LEF1 and the formation of the β-catenin/LEF1 complex, which is crucial for Wnt target gene regulation in SW480 tumor cells." (PMID 38003292, 2023). "LCA can inhibit the STIP1/AHCY/LDHA axis and inhibit tumor development mediated by the gly." (PMID 41163796, 2025). "However, genes AHCY (adenosylhomocysteinase), DPYSL3 (dihydropyrimidinase like 3), and NME1 (NME/NM23 nucleoside diphosphate kinase 1) are involved in this tumour development." (PMID 38542729, 2024). "Indeed, we found that the expression of metabolic enzymes MTR, AHCY, and SHMT2 was elevated in tumorspheres compared to adherent tumor cells, which supports the idea that hypoxia is a key factor in altering the pattern of one-carbon metabolism in tumorsphere cells." (PMID 39872059, 2023).
infection (8 papers, 2010 to 2024). The state of being infected such as from the introduction of a foreign agent such as serum, vaccine, antigenic substance or organism. "In particular, the adenosylhomocysteinase (AHCY) inhibitor DZNep is antiviral in in vitro, in ex vivo, and in a mouse infection model and synergizes with existing COVID‐19 treatments." (PMID 35833542, 2022). "In vivo efficacy of AHCY inhibitors is remarkable, as a single dose of either of the three distinct AHCY inhibitors 3-deazaneplanocin A, 3-deazaaristeromycin, or 3-deazaadenosine protects mice against a lethal infection of the Ebola virus (subtype Zaire)." (PMID 33869213, 2021). "Meanwhile, the infection increased the mRNA transcription of MAT2A, AMD1, SMS, and AHCY mRNA with the same MOI." (PMID 38130504, 2024). "Notably, the SAM cycle inhibitor 3‐deazaneplanocin A (DZNep), an inhibitor of AHCY, has especially potent and selective antiviral efficacy against SARS‐CoV‐2 in in vitro, in ex vivo, and in a mouse infection model." (PMID 35833542, 2022).
immune diseases (1 paper, 2016). "The use of AHCY inhibitors for therapeutic purposes in inflammatory and immune diseases is being studied, since inhibition of AHCY is associated with immunosuppression." (PMID 27104343, 2016).
AHCY also shares sentences with these, for which no sentence is quoted: endothelial dysfunction (3 papers); hyperhomocysteinemia (3); liver cancer (3); tuberculosis (3); atherosclerosis (2); colorectal adenocarcinoma (2); diabetes (2); diabetic cardiomyopathy (2); intestinal tumor (2); leukemia (2); liver disease (2); lung carcinoma (2); malaria (2); myopathy (2); renal carcinoma (2); Wilson disease (2); autoimmune disease (1); cardiovascular diseases (1); citrin deficiency (1); CNS tumors (1); colitis (1); colorectal (1); dementia (1); developmental delay (1); diabetic nephropathy (1); Down syndrome (1); endometrial cancer (1); esophageal cancer (1); gastric cancer (1); glioblastoma (1).
A further 23 diseases each share a sentence with AHCY in 1 paper.